ITPR2 (inositol 1,4,5-trisphosphate receptor type 2)
Description:
Inositol 1,4,5-trisphosphate-gated calcium channel that upon inositol 1,4,5-trisphosphate binding transports calcium from the endoplasmic reticulum lumen to cytoplasm. Exists in two states; a long-lived closed state where the channel is essentially 'parked' with only very rare visits to an open state and that ligands facilitate the transition from the 'parked' state into a 'drive' mode represented by periods of bursting activity (By similarity).
Synonyms: InsP3R2; IP3R2; CFAP48; ANHD
Tractability: Small molecule: a high-quality ligand is known; it belongs to a druggable protein family. Antibody: its Gene Ontology location is reachable by antibodies, with high confidence; UniProt predicts a signal peptide or a membrane-spanning region. PROTAC: ubiquitination databases record sites on it; its protein half-life has been measured; a small molecule that binds it is known.
Gene: Protein-coding gene on chromosome 12 (26,335,352 to 26,833,194, reverse strand). Ensembl gene ENSG00000123104.
Subcellular location: Endoplasmic reticulum membrane; Cytoplasmic vesicle, secretory vesicle membrane
Subcellular location (Human Protein Atlas): Endoplasmic reticulum; Mid piece; End piece; Nucleoplasm; Principal piece
Pathways (Reactome):
Immune System: Antigen activates B Cell Receptor (BCR) leading to generation of second messengers; CLEC7A (Dectin-1) induces NFAT activation; FCERI mediated Ca+2 mobilization; Role of phospholipids in phagocytosis
Signal Transduction: Ca2+ pathway; DAG and IP3 signaling; PLC beta mediated events; VEGFR2 mediated cell proliferation
Hemostasis: Effects of PIP2 hydrolysis; Elevation of cytosolic Ca2+ levels
Metabolism: Glucagon-like Peptide-1 (GLP1) regulates insulin secretion; Regulation of insulin secretion
Disease: FCGR3A-mediated IL10 synthesis
Muscle contraction: Ion homeostasis
Gene Ontology:
Molecular function: protein binding; scaffold protein binding; transmembrane transporter binding; calcium ion binding; calcium ion transmembrane transporter activity; inositol 1,4,5 trisphosphate binding; inositol 1,4,5-trisphosphate-gated calcium channel activity; phosphatidylinositol binding; calcium channel activity; intracellularly gated calcium channel activity; monoatomic ion channel activity
Biological process: response to hypoxia; release of sequestered calcium ion into cytosol; signal transduction; calcium ion transmembrane transport; calcium ion transport; calcium-mediated signaling; cellular response to cAMP; monoatomic ion transport; transmembrane transport
Cellular component: membrane; plasma membrane; receptor complex; sarcoplasmic reticulum membrane; endoplasmic reticulum membrane; platelet dense tubular network membrane; sarcoplasmic reticulum; secretory granule membrane; cell cortex; cytoplasm; endoplasmic reticulum; transport vesicle membrane
Genetic constraint (gnomAD): Loss-of-function variants: 137 observed, 218.12 expected, observed/expected ratio (o/e) 0.63, 90% interval 0.55 to 0.72. The upper end of that interval is the gene's LOEUF score, 0.72, which puts it in group 2 of 6, group 1 being the genes least tolerant of losing a copy. Missense variants: 2,084 observed, 2,725.3 expected, observed/expected ratio (o/e) 0.76, 90% interval 0.74 to 0.79. Synonymous variants: 953 observed, 975.48 expected, observed/expected ratio (o/e) 0.98, 90% interval 0.93 to 1.03.
Homologues: Orthologues: chimpanzee ITPR2 (99% identical), macaque ITPR2 (99% identical), dog ITPR2 (98% identical), pig ITPR2 (97% identical), mouse Itpr2 (96% identical), rabbit ITPR2 (95% identical), rat Itpr2 (95% identical), guinea pig ITPR2 (94% identical), tropical clawed frog itpr2 (88% identical), zebrafish itpr2 (55% identical), Drosophila melanogaster RyR (21% identical), Caenorhabditis elegans unc-68 (21% identical). Paralogues in human: ITPR1 (69% identical), ITPR3 (65% identical), RYR2 (25% identical), RYR1 (25% identical), RYR3 (25% identical).
Diseases named in the same sentence as ITPR2 in open-access papers:
ITPR2 is named in the same sentence as 101 diseases in open-access papers, as found by Europe PMC text mining. Sharing a sentence is not in itself a finding about the gene and the disease. The quoted sentences say what the papers report.
Anxiety (7 papers, 2014 to 2025). Intense feelings of nervousness, tension, or panic often arise in response to interpersonal stresses. "Together, these results suggest that Itpr2 loss in oligodendrocytes may induce anxiety and depressive‐like behaviors in the animals, thus strengthening the significance of OL calcium homeostasis in mediating neural functions." (PMID 38476116, 2024). "In current study, two lines of oligodendrocyte‐specific Itpr2 knockout mice were generated, and both Itpr2 cKO and Itpr2 iKO mice showed impaired myelination and anxiety/depressive‐like behaviors." (PMID 38476116, 2024). "Our results showed that ITPR2‐mediated calcium homeostasis is required for proper development of OPCs, and conditional ablation of Itpr2 in OLs leads to anxiety and depressive‐like behaviors in the animals." (PMID 38476116, 2024). "Animals with OL‐specific deletion of Itpr2 exhibit anxiety/depressive‐like behaviors and manifest with interrupted OPC proliferation, leading to fewer mature OLs in the brain." (PMID 38476116, 2024). "As patients with anxiety are often accompanied by depression, we then examined the depressive like behaviors in Itpr2 cKO mice." (PMID 38476116, 2024). "Additionally, we tested the anxiety and depressive behaviors in Itpr2 cKO mice after the TUDAC application." (PMID 38476116, 2024). "Mice with Itpr2 deletion in vHPC astrocytes were subjected to SRS and anxiety‐like behavioral tests were done before and after SRS." (PMID 39120568, 2024). "Itpr2 mutant at P45 treated with TUDCA revealed decreased immobility time than vehicle‐treated mutant in tail resuspension test, indicating the alleviated anxiety/depressive mood in these mice." (PMID 38476116, 2024). "Astrocytes solitarily express inositol 1,4,5-trisphosphate receptor type 2 (IP3R2/ITPR2), and ITPR2 conditional knockout mice do not display anxiety or depression-like behavior or changes in motor and sensory function." (PMID 37363320, 2023).
depression (7 papers, 2016 to 2024). "The knockout of ITPR2 led to abnormalities in the striatum, a key component of the emotion-regulating network in mice, which may be related to the depression-like behavior associated with ITPR2 deficiency." (PMID 39518882, 2024).
heart failure (7 papers, 2009 to 2025). Inability of the heart to pump blood at an adequate rate to meet tissue metabolic requirements. "ITPR2 has been found to be highly expressed in cardiomyocytes and to be associated with human heart failure." (PMID 34727889, 2021). "The alteration in ITPR2 is coupled with initiation and/or progression of hypertrophy and heart failure." (PMID 21791083, 2011).
anhidrosis (6 papers, 2020 to 2025). Lack of sweating or the ability to sweat when provoked by the appropriate stimulus. "Previously, there was only one variant in ITPR2 reported in OMIM-database [p.(Gly2498Ser)] that causes AR anhidrosis with normal sweat gland in one family (OMIM #106190)." (PMID 33710394, 2021). "Previously, there was only one variant [p.(Gly2498Ser)] reported in ITPR2 that causes AR anhidrosis with normal sweat gland in one family (OMIM #106190)." (PMID 33710394, 2021). "A homozygous missense variant in ITPR2 has been reported to cause isolated anhidrosis." (PMID 39804930, 2025). "Interestingly, mutations of ITPR2 have been associated with anhidrosis, such as critically low levels of perspiration, indicating a mechanism that could potentially be pathophysiologically meaningful for PFH aetiology." (PMID 33378362, 2020). "Mutations in ITPR2 and ITRP3, respectively, encoding IP3R types 2 and 3, are associated with anhidrosis in patients, and the same phenotype is also observed in Itpr2 and Itpr3 double knockout mice." (PMID 33250786, 2020).
Ataxia (5 papers, 2014 to 2025). Ataxia refers to impaired coordination of voluntary muscle movement. "Itpr1 knockout mice either died in utero or had severe ataxia and epilepsy after birth, whereas Itpr2 knockouts had reduced sweat secretion and Itpr3 knockouts had abnormal taste perception." (PMID 39804930, 2025). "IP3R channel dysfunction has been associated with several disorders, such as spinocerebellar ataxia, Gillepsie syndrome, and generalized anhidrosis, mainly due to variants in ITPR1 and ITPR2." (PMID 39560673, 2025).
lung carcinoma (4 papers, 2016 to 2025). "We first assessed associations between the expression values of all ITPRs (ITPR1, ITPR2, ITPR3) and overall survival in lung cancer patients." (PMID 35625784, 2022). "Interestingly, SplitFusion detected novel fusions that have not been reported previously in lung cancer, including one squamous cell carcinoma with FGFR3::JAKMP1 fusion, one adenocarcinoma with CLIP2::BRAF fusions (two fusion isoforms in one tumor), and one adenocarcinoma with ITPR2::ETV6 fusion." (PMID 40041857, 2025).
acute myeloid leukemia (3 papers, 2015 to 2022). Acute myeloid leukemia (AML) is a group of neoplasms arising from precursor cells committed to the myeloid cell-line differentiation. "ITPR2 was found to participate in acute myeloid leukemia and clear cell renal cell carcinoma progression." (PMID 35580861, 2022). "However, the clinical impact of ITPR2 in cytogenetically normal acute myeloid leukemia (CN-AML) remained unknown." (PMID 25779662, 2015).
Kashin-Beck disease (3 papers, 2015 to 2022). Disabling osteochondrodysplasia with osteosclerosis, cone-shaped metaphysis, and shortening of the diaphysis. "Moreover, there are experimental results showing that the locus ITPR2-rs11048570 is significantly associated with Kashin-Beck Disease in the Han Chinese." (PMID 36686460, 2022). "Recently, a genome-wide association study in humans identified ITPR2 as a susceptibility gene for Kashin-Beck disease which is a chronic osteochondropathy, mainly characterized by cartilage degeneration, cartilage matrix degradation, chondrocyte necrosis and apoptosis." (PMID 26228268, 2015). "Of note, a recent GWAS in a Chinese population identified ITPR2 as a susceptibility gene for the Kashin-Beck disease, a chronic osteochondropathy characterized by cartilage degeneration; in this study, a significant association between the disease and nine SNPs of ITPR2 was described." (PMID 32290556, 2020). "Interestingly, the regulatory role of ITPR2 in apoptosis is a possible contributor to the Kashin-Beck disease, since excessive chondrocyte apoptosis was found to be related to cartilage lesions in affected patients." (PMID 32290556, 2020).
Arrhythmia (2 papers, 2022 to 2024). Any cardiac rhythm other than the normal sinus rhythm. "In addition, ITPR2 overexpression has been linked to many cardiac pathologies including cardiac arrhythmias, failure and hypertrophy." (PMID 36555856, 2022).
asthma (2 papers, 2023 to 2026). "Similarly, endothelin pathway mediators played an important role in initiating eosinophilic inflammation after allergen, and polymorphisms in the endothelin signaling protein ITPR2 are associated with asthma in humans." (PMID 37814791, 2023). "Differentially methylated loci were near genes related to asthma (ITPR2, MAPK1), lung function (FKBP11), mitochondrial function (MRPL20, SPTBN1), inflammation (C3), and immune function (N4BP3, EIF5)." (PMID 41749276, 2026).
bipolar disorder (2 papers, 2016 to 2022). A disorder of the brain that causes unusual shifts in mood, energy, activity levels and the ability to carry out day-to-day tasks. "Likewise, the profiles of genes in the inositol 1,4,5-trisphosphate receptor family, including ITPR1, ITPR2, and ITPR3, were impacted by MIA, and members of this family have been associated with neurological and motor function impairment and bipolar disorder." (PMID 36011282, 2022).
glioma (2 papers, 2013 to 2025). A benign or malignant brain and spinal cord tumor that arises from glial cells (astrocytes, oligodendrocytes, ependymal cells). "MCOLN2, TRPV4, and ITPR2 were significantly highly expressed in glioma tissues, and the three most significantly down-regulated genes (PRKCG, CAMK2A, and HTR2A) had lower expression in tumor tissues." (PMID 41331166, 2025).
Hepatic steatosis (2 papers, 2022 to 2025). Steatosis is a term used to denote lipid accumulation within hepatocytes. "However, several works indicated that IP3R2 was a driver of senescence in human cells, and ITPR2 knockout mice had suppressed Ca2+ fluxes in the MAM region and displayed less immunosenescence as well as less hepatic steatosis and fibrosis." (PMID 36686460, 2022).
lymphoma (2 papers, 2017 to 2020). A malignant (clonal) proliferation of B- lymphocytes or T- lymphocytes which involves the lymph nodes, bone marrow and/or extranodal sites. "Notably, all five ITPR2 mutations found in NMZLs were clustered within the MIR domain of ITPR2, whereas ITPR2 mutations previously reported in other types of lymphomas at lower frequencies were located at other sites." (PMID 32585984, 2020). "Notably, ITPR2 mutations identified in NMZLs were clustered within the MIR domain, unlike other types of lymphoma." (PMID 32585984, 2020).
malignant melanoma (2 papers, 2020 to 2025). "Mutations in ITPR2 have been reported in various types of solid tumors, including endometrial carcinoma (9.3%), malignant melanoma (6.4%), urothelial carcinoma (7.0%), and rarely in lymphoid neoplasm including DLBCL (3.0–7.5%), multiple myeloma (1.5%), CLL (0.2%), and a case with Sezary syndrome." (PMID 32585984, 2020).
schizophrenia (2 papers, 2018 to 2019). A major psychotic disorder characterized by abnormalities in the perception or expression of reality. "Nonetheless, a subset of PD (e.g., SLC50A1), ALS (ITPR2), and schizophrenia (RENBP) susceptibility genes were part of the microglia signature in the aged human brain." (PMID 29416036, 2018).
steatosis (2 papers, 2021 to 2022). Increased lipid within the cytoplasm of cells. "ITPR1 and ITPR2 may thus promote senescence and subsequent key drivers of age-related defects in the liver, including steatosis and alterations of glucose homeostasis." (PMID 33526781, 2021). "In line with this hypothesis, Itpr2 KO delays age-related features of the liver, including both steatosis and fibrosis." (PMID 33526781, 2021). "Compared to WT mice, the livers of old Itpr2 KO mice displayed no marks of macroscopic steatosis and fewer lipid droplets." (PMID 33526781, 2021). "Furthermore, one study showed that ITPR2 expression was significantly reduced or absent in patients with steatosis and NASH." (PMID 36686460, 2022).
bladder cancer (1 paper, 2021). "From our work in this research, we demonstrated the oncogenic role of ITPR3 in bladder cancer in contrast to the roles of ITPR1 and ITPR2, whose proapoptotic effect was already described." (PMID 33573671, 2021). "We also found that ITPR1 was expressed at low levels in bladder cancer, while there was no obvious difference in ITPR2 expression compared with normal expression which was consistent with the result of western-blot." (PMID 33573671, 2021).
colorectal cancer (1 paper, 2023). A primary or metastatic malignant neoplasm that affects the colon or rectum. "(A) T1 colorectal cancer (CRC) samples from a set of 47 cases were used to verify the abundance of ABI1, ITPR2, RHOT2, ATAD2, and ISLR." (PMID 37158593, 2023).
endothelial dysfunction (1 paper, 2012). In vascular diseases, endothelial dysfunction is a systemic pathological state of the endothelium (the inner lining of blood vessels) and can be broadly defined as an imbalance between vasodilating and vasoconstricting substances produced by (or acting on) the endothelium. "Prior candidate gene studies have associated SNPs in ITPR2 with markers of inflammation and endothelial dysfunction as well as blood pressure phenotypes." (PMID 23155414, 2012).
Hyperhidrosis (1 paper, 2020). Abnormal excessive perspiration (sweating) despite the lack of appropriate stimuli like hot and humid weather. "This association was corroborated by the observation of anhidrosis and hyperhidrosis in human pathologies linked to ITPR dysfunction; also, there was a marked reduction of sweat secretion in ITPR2-/- animals." (PMID 32290556, 2020). "Interestingly, ITPR2 inhibitors have the potential to reduce sweat production in hyperhidrosis, suggesting that ITPR2 is a potential pharmacological target in the treatment of sweat secretion conditions." (PMID 32290556, 2020).
Hypertension (1 paper, 2020). The presence of chronic increased pressure in the systemic arterial system. "RCC risk has been found to be associated with interactions between alcohol consumption and ADH726; sodium and hypertension and AGTR, AGT and ACE31; calcium and vitamin D intake and RXRA28; tobacco smoking and NAT2, CYP1A1 and GSTM125; and meat-cooking mutagens and ITPR2 and EPAS127." (PMID 31924838, 2020).
liver diseases (1 paper, 2024). "Consequently, liver diseases in which ITPR2 is reduced result in impairments in both bile secretion and liver regeneration." (PMID 38916955, 2024).
pancreatic cancer (1 paper, 2022). "Secondly, we used Kaplan-Meier Plotter and GEPIA databases to explore the prognostic value of ITPRs in pancreatic cancer: decreased ITPR2 and ITPR3 indicated better survival." (PMID 35580861, 2022). "Up-regulated ITPR2 and ITPR3 were associated with higher pathological stages of pancreatic cancer." (PMID 35580861, 2022). "As Kaplan-Meier Plotter analysis demonstrated, decreased expression of ITPR2 and ITPR3 indicated better overall survival for patients with pancreatic cancer." (PMID 35580861, 2022). "To evaluate the function of ITPRs on the cancer patient’s clinicopathological and survival, we investigated survival analysis of ITPR1, ITPR2, and ITPR3 for pancreatic cancer by using Kaplan-Meier Plotter and GEPIA databases." (PMID 35580861, 2022). "This study found that ITPR1 and ITPR3 were up-regulated in pancreatic cancer, while there was no significant change in ITPR2." (PMID 35580861, 2022).
parasitic infection (1 paper, 2022). "Jaw1 and ITPR2 are expressed in small intestinal tuft cells, chemosensory cells that detect parasitic infection, Jaw1 and ITPR3 in tongue epithelial taste cells that perceive taste, and Jaw1 and ITPR2/3 in pancreatic acinar cells that secrete digestive enzymes." (PMID 35676525, 2022).
parathyroid disease (1 paper, 2025). "Although classified as VUS, several candidate genes previously reported to be associated with parathyroid disease, including ITPR2, IL21R, MMP14, TWIST1 and ESR2 were identified in three patients with cancer-type tumors." (PMID 40434298, 2025).
prostate carcinoma (1 paper, 2023). A carcinoma that arises from epithelial cells of the prostate gland. "After constructing the prognostic prediction model, SLPI, VSIG2, CENPF, SLC7A1, SMC4, and ITPR2 were finally regarded as the key genes in the prognosis of patients with prostate cancer." (PMID 36937411, 2023).
pulmonary hypertension (1 paper, 2022). Increased pressure within the pulmonary circulation due to lung or heart disorder. "ITPR2 increases intracellular calcium concentration in vascular smooth muscle and it controls vasoconstriction avoiding pulmonary hypertension." (PMID 36568400, 2022).
sporadic amyotrophic lateral sclerosis (1 paper, 2016). Sporadic amyotrophic lateral sclerosis is a amyotrophic lateral sclerosis in which there is no known cause, such as no family history. "ITPR2 has been identified as a susceptibility gene in sporadic amyotrophic lateral sclerosis, possibly via its role in glutamate-mediated neurotransmission." (PMID 26852023, 2016).